CHST13 (carbohydrate sulfotransferase 13)
Description:
Catalyzes the transfer of sulfate to position 4 of the N-acetylgalactosamine (GalNAc) residue of chondroitin. Chondroitin sulfate constitutes the predominant proteoglycan present in cartilage and is distributed on the surfaces of many cells and extracellular matrices. Transfers sulfate to the C4 hydroxyl of beta1,4-linked GalNAc that is substituted with a beta-linked glucuronic acid at the C-3 hydroxyl. No activity toward dermatan.
Synonyms: C4ST3
Tractability: Antibody: UniProt predicts a signal peptide or a membrane-spanning region. PROTAC: its protein half-life has been measured.
Gene: Protein-coding gene on chromosome 3 (126,524,155 to 126,543,291, forward strand). Ensembl gene ENSG00000180767.
Subcellular location: Golgi apparatus membrane
Subcellular location (Human Protein Atlas): Golgi apparatus
Pathways (Reactome):
Metabolism: CS-GAG biosynthesis
Gene Ontology:
Molecular function: chondroitin 4-sulfotransferase activity; dermatan 4-sulfotransferase activity; protein binding; sulfotransferase activity
Biological process: chondroitin sulfate proteoglycan biosynthetic process; proteoglycan biosynthetic process; carbohydrate biosynthetic process; glycoprotein biosynthetic process
Cellular component: Golgi membrane; membrane; Golgi apparatus
Genetic constraint (gnomAD): Loss-of-function variants: 1 observed, 4.4 expected, observed/expected ratio (o/e) 0.23, 90% interval 0.08 to 1.07. That is too few expected variants to judge how well the gene tolerates losing a copy. Missense variants: 539 observed, 356.06 expected, observed/expected ratio (o/e) 1.51, 90% interval 1.41 to 1.63. Synonymous variants: 235 observed, 169.05 expected, observed/expected ratio (o/e) 1.39, 90% interval 1.25 to 1.55.
Homologues: Orthologues: chimpanzee CHST13 (99% identical), macaque CHST13 (94% identical), dog CHST13 (83% identical), pig CHST13 (82% identical), guinea pig CHST13 (79% identical), rat Chst13 (79% identical), mouse Chst13 (78% identical), rabbit CHST13 (77% identical), zebrafish chst13 (52% identical). Paralogues in human: CHST11 (48% identical), CHST8 (35% identical), CHST12 (34% identical), CHST14 (34% identical), CHST9 (30% identical), CHST10 (26% identical).
Diseases named in the same sentence as CHST13 in open-access papers:
CHST13 is named in the same sentence as 12 diseases in open-access papers, as found by Europe PMC text mining. Sharing a sentence is not in itself a finding about the gene and the disease. The quoted sentences say what the papers report.
hepatocellular carcinoma (2 papers, 2021). A malignant tumor that arises from hepatocytes. "For example, the expressions of CHST11 and CHST13 increased in human hepatocellular carcinoma tissues than in adjacent tissues and promoted metastasis and drug resistance by activating the MAPK pathway." (PMID 34288811, 2021). "In hepatocellular carcinoma, downregulation of CHST13 regulates the metastasis and chemosensitivity of human hepatocellular carcinoma cells via the mitogen-activated protein kinase (MAPK) pathway." (PMID 33708772, 2021).
Crohn disease (1 paper, 2023). A gastrointestinal disorder characterized by chronic inflammation involving all layers of the intestinal wall, noncaseating granulomas affecting the intestinal wall and regional lymph nodes, and transmural fibrosis. "Our findings suggest that CHST13 may be involved in the pathogenesis of pediatric Crohn’s disease, potentially through its role in extracellular matrix homeostasis and tissue repair." (PMID 36936436, 2023).
glioma (1 paper, 2021). A benign or malignant brain and spinal cord tumor that arises from glial cells (astrocytes, oligodendrocytes, ependymal cells). "Furthermore, CHST11 and CHST13 have been reported as oncogenes in gliomas." (PMID 34288811, 2021).
leukemia (1 paper, 2021). A malignant (clonal) hematologic disorder, involving hematopoietic stem cells and characterized by the presence of primitive or atypical myeloid or lymphoid cells in the bone marrow and the blood. "Among the metabolic genes downregulated in NPM1/cohesin-mut compared with NPM1-mut AML, CHST13, ADCY9, PRR16, LPL, and SLC1A3 were confirmed by STAG2-deficient model of NPM1-mut leukemia." (PMID 34193978, 2021).
osteosarcoma (1 paper, 2023). A usually aggressive malignant bone-forming mesenchymal neoplasm, predominantly affecting adolescents and young adults. "More interestingly, the expression of several of these genes, including CHST13, FKBP11, SGMS2, TRPS1, PRKX, SP7, and DNAJC1, were highly associated with osteosarcoma prognosis." (PMID 37457661, 2023).
ovarian carcinoma (1 paper, 2022). A malignant neoplasm originating from the surface ovarian epithelium. "The mRNA expression of CHST13 was found to be significantly higher in in ovarian cancer specimens than in non-malignant tumor specimens." (PMID 36618366, 2022).
prostate carcinoma (1 paper, 2022). A carcinoma that arises from epithelial cells of the prostate gland. "CHST12, CHST13, and CHST14 can also mediate C4S sulfations under some circumstances, however, these enzymes did not respond to castration in the prostate cancer progression PDX model." (PMID 35963852, 2022).
cancer (3 papers, 2022 to 2024). A tumor composed of atypical neoplastic, often pleomorphic cells that invade other tissues. "Previous researches suggested that CHST13 is prominently associated with several biological processes, including liver injury, cell invasion, and cancer; however, the correlation between CHST13 and adipose deposition remains largely unexplored and warrants further research." (PMID 37662841, 2023). "Finally, we found major differences among the cancer cell lines in their expression of genes involved in glycosylation, including CHST11, CHST13, Ext1, HAS2 and HAS3, which may have an impact on the architectural organization of the spheroids." (PMID 39011470, 2024).
tumor (2 papers, 2021 to 2022). "Other ofCS modification enzymes (DSE, CHST11, and CHST13) were not differentially expressed between normal and tumor samples." (PMID 34966741, 2021).
CHST13 also shares sentences with these, for which no sentence is quoted: breast carcinoma (1 paper); colorectal cancer (1); infection (1).